SST (somatostatin)
Diseases named in the same sentence as SST in open-access papers (continued):
Sharing a sentence is not in itself a finding about the gene and the disease.
tumor (continued). "The methylation levels in tumor samples of the digestive system from TCGA were concomitantly significantly higher compared to normal tissue suggesting SST hypermethylation as a general mechanism of somatostatin downregulation in these types of tumors." (PMID 32243066, 2020). "For all cancers, a comparison of tumor and healthy tissue samples revealed significant SST hypermethylation in tumor, implying that SST hypermethylation is a general and common feature in a broad range of tumors and could be utilized as a pan‐cancer biomarker." (PMID 32243066, 2020). "It is therefore possible that an enhanced ability of the chimeric TBR-760 to bind with greater affinity or modulate activity of these heterodimers may contribute to the greater effect on tumor growth than the DA or SST agonists alone or in combination." (PMID 32591776, 2020). "The specific intracellular pathways activated by SRLs, as well as their potency, is different in the different tumor types, depending on the specific SST distribution pattern, as well as signaling elements, receptor desensitization, internalization, and cross talk." (PMID 31412614, 2019). "Several anti-tumor effects of SST and SST analogues have been described in HCC." (PMID 31569719, 2019). "This could be due to differences in trial design, different dose and type of SST analogues, different patient populations, but also differences in tumor biology including SSTR expression by the tumor or surrounding tissue." (PMID 31569719, 2019). "Pancreatic islet hyperplasia and co‐secretion of insulin (in addition to somatostatin) from tumour cells, respectively, have been characterized as completely distinct mechanisms of hypoglycaemia at both the functional and morphological levels in these two patients." (PMID 31592116, 2019). "Moreover, in the last few years 18F-fluorodeoxyglucose ([18F]FDG) PET/CT has emerged as an important tool to define tumor aggressiveness and give relevant prognostic information, particularly when coupled with [68Ga]Ga-labelled SST analogues PET/CT." (PMID 31337043, 2019). "The clinical presentation can be due to symptoms related to hormone over-secretion by the tumor, such as excess insulin (insulinoma), gastrin (gastrinoma), glucagon (glucagonoma), vasoactive intestinal peptide (VIPoma), somatostatin (somatostatinoma), or pancreatic polypeptide (PPoma)." (PMID 31207914, 2019). "The vast majority of these tumors express somatostatin (SST) receptors (SSTR) on tumor the cell surface, a feature that may be used for both diagnostic and therapeutic purposes." (PMID 31337043, 2019). "The limited efficacy of pasireotide may reflect the unique biology of pasireotide binding to SSTR2 subtype, which has been shown to be critical for the growth inhibitory effects of somatostatin signaling pathway in various tumor types." (PMID 30807575, 2019). "The third approved indication for SST analogs in patients with NETs is for imaging of the tumor." (PMID 30008698, 2018). "Somatostatin could be involved in tumor growth suppression, as confirmed by the use of SST analogs to treat neuroendocrine tumors." (PMID 29949880, 2018). "The first results indicating that high-affinity SST antagonists that poorly internalize into tumor cells perform more effectively than corresponding agonists that are highly internalized into tumor cells were considered to be at the forefront of a paradigm shift in nuclear oncology imaging." (PMID 30232095, 2018). "The high incidence of SST receptors in UM suggests that this type of tumor might be a good candidate for therapy with SST analogs including the targeted cytotoxic peptide AN-162." (PMID 29949880, 2018). "Moreover, by various mechanisms, SST has the potential to suppress tumor growth in a variety of cancers." (PMID 29854027, 2018). "In particular, SST analogs (SSA) are used frequently to control hormone-related symptoms in NE cancer patients while their anti-neoplastic activity seems to result prevalently in tumor stabilization." (PMID 28194370, 2017).
tumor (continued). "Since the other SSTRs were present at much lower levels, pan-somatostatin analogs appear to be less appropriate to control tumor progression, but SST2A-selective drugs may benefit from a limited side-effect profile." (PMID 29163802, 2017). "In addition, somatostatin is a widely distributed neuropeptide with multiple physiological functions, including immune regulation and tumour suppression." (PMID 28430638, 2017). "The effects of serum methylation of SST were also investigated based on tumor stages." (PMID 28187169, 2017). "SHP1 activation by SST induces the arrest of cell proliferation in numerous tumor cell lines." (PMID 28903425, 2017). "Interestingly, under obese conditions, SST-KO exhibited a remarkable increase in tumor incidence compared to lean SST-KO (26.66 % vs 4.34 %; p <0.001) and to their HF-fed WT counterparts." (PMID 26956474, 2016). "In addition, obese SST-KO mice had increased tumor multiplicity (p = 0.053) and ductal mammary hyperplasia compared to lean, LF-fed SST-KO mice, and a concomitantly lower percentage of normal MGs." (PMID 26956474, 2016). "Beside its inhibitory effects on tumor cells, somatostatin could affect tumor progression by impacting on the stromal compartment." (PMID 27177087, 2016). "Long acting somatostatin analogs may control ectopic hormonal secretion syndrome, and restrict tumor growth." (PMID 27349224, 2016). "In addition to inhibiting insulin release and elevating blood glucose levels, somatostatin analogues also have anti-proliferative and tumour-stabilising effects." (PMID 25755880, 2015). "Since SSTR2 has been known to be most commonly expressed in various NETs and possesses the highest affinity for natural SST and synthetic SST analogs, most experiments utilize hSSTr2 reporter gene to transfect targeted tumor cells alone or together with other therapeutic genes." (PMID 25879040, 2015). "The loss of SSTR 2 may consequently promote tumor growth and make it clear the therapeutic inefficacy of SST analogs in such kind of neoplasia." (PMID 24570674, 2014). "However, data on the effect of SST analogs on tumor growth in patients with gastric carcinoids type C or poorly differentiated endocrine carcinomas are scanty." (PMID 24570674, 2014). "Of course, the evidence of a high uptake of 68Ga-labeled SST-analogues could be used to accurately define the tumor biology “map” and therefore may be potentially helpful in selecting the most appropriate therapeutic option." (PMID 24693229, 2014). "SST ability of inhibiting tumor growth and metastatic spread involves SST receptor activation located on both cancer and microenvironment cells, particularly endothelial cells of tumor vessels responsible of the neovascularization of the tumor." (PMID 23476673, 2013). "Tumor cells were stained for chromogranin A, synaptophysin and somatostatin." (PMID 23618063, 2013). "Furthermore, the current study demonstrated that SST mRNA expression was significantly lower in the tumor group (0.218±0.183) compared with that in the normal group (0.456±0.331), as measured using RT-PCR." (PMID 24260078, 2013). "When correlating the transcripts that were verified in the total patient population with important clinical parameters, including tumor size, acute somatostatin test, reduction in IGF-I levels (%) and tumor size reduction (%), several significant correlations were found." (PMID 23825587, 2013). "Indeed, SST is a powerful inhibitor of neovascularization in several experimental models and, consequently, the inhibition of tumor angiogenesis is considered one of the mechanisms mediating SST antineoplastic effects." (PMID 23476673, 2013). "In fact, starting from the identification of the expression, and in some cases overexpression, of these receptors in several human tumors, several clinical trials were performed to assess the possible clinical efficacy of SST agonists in almost all tumor types." (PMID 23476673, 2013).
tumor (continued). "Employing SST and its analogues in combination with chemotherapeutic agents might provide an additional tool to target tumours in multiple ways or to provide synergistic anti-tumor actions." (PMID 24281555, 2012). "The radioactive octreotide attaches to tumor cells that have receptors for somatostatin." (PMID 23316341, 2012). "Moreover, the heterodimerization of SSTR2 with mutated SST5TMD4 modulates SSTR2 regulated downstream signaling and SST mediated anti-tumor effects." (PMID 24281555, 2012). "The loss of SSTR 2 may consequently promote tumour growth and make it clear the therapeutic inefficacy of SST analogues in such kind of neoplasia." (PMID 20196864, 2010). "The tumor cells showed positive reactivity for synaptophysin, somatostatin, and CD56." (PMID 20444291, 2010). "Irregular serotonin and somatostatin immunoreactivity in these tumours was reported earlier." (PMID 18252007, 2008). "Fifty-seven out of 63 (90%) of malignant and 26/35 (74%) benign tumours expressed somatostatin." (PMID 12085262, 2002). "However, the somatostatin peptide-hormone is subject to rapid enzymatic degradation in vivo, motivating attempts to develop synthetic somatostatin analogues (SSAs) in order to provide tumour targeting with sufficient stability and affinity." (PMID 38543120, 2024). "In addition to these prominent angiogenesis inhibitors, SST, which is widely distributed at a high density in different tumours and plays an antiproliferative role in tumours either directly or indirectly, has also been reported as a potential inhibitor of angiogenesis." (PMID 38203605, 2023). "Taken together, these observations attest to the significant role of SST in regulation of tumour growth or cell proliferation and the modulation of tumour promoting downstream signaling molecules; thus, it serves as potential therapeutic intervention in tumour biology." (PMID 38203605, 2023). "Therefore, our primary aim was to test whether total somatostatin expressing tumour volume, defined either as ∑SRETV or ∑TLSRE measured on PET‐CT images, was correlated with QLQ‐C30 summary scores in patients with metastatic GEP‐NET." (PMID 35488399, 2022). "Furthermore, the idea of combining somatostatin with radiation was developed so that the radiation dose could be directly delivered to the tumor tissue." (PMID 35566491, 2022). "These endocrine cells are characterized by the expression of SST, and differences in the number of these cells in normal and tumor tissue, and thus the level of SST expression, may bias the conclusions focusing on downregulated SST expression levels in tumor tissue." (PMID 33085037, 2021). "SST gene expression may simultaneously discriminate tumor from inflammation (AUC = 0.74)." (PMID 32243066, 2020). "However, the combination of these imaging agents might provide higher diagnostic accuracy, e.g., [18F]FDG is used for measuring the tumor metabolic rate whereas [68Ga]Ga-SST provides information on SSTR expression guiding the biopsy." (PMID 32151049, 2020). "Thus, imaging at later time points enables further increase of imaging contrast, and hence sensitivity, even for imaging probes with rapid in vivo kinetics and tumor targeting, such as bombesin analogues, somatostatin analogues, single chain variable fragments (scFv), and affibody molecules." (PMID 32183096, 2020). "Somatostatin (somatotropin release-inhibiting hormone, SST), a small polypeptide hormone produced in the hypothalamus, regulates endocrine function mainly by suppressing the release of hormones and neurotransmitters and inhibits tumor growth by regulating tumor cell survival and angiogenesis." (PMID 33045023, 2020). "In fact, this result indicating that silencing of GPR107 may inhibit cell proliferation/migration via negative regulation of AKT pathway is a common mechanism that has been previously reported with other components of the somatostatin system in different tumor types, including PCa." (PMID 32498336, 2020).
tumor (continued). "Metastatic tumor masses along with the production of peptide hormones, such as gastrin, somatostatin, insulin, glucagon, or vaso inhibitory peptide (VIP) by tumor cells, may lead to severe symptoms and complications, such as diarrhoea, gastric ulcers, flush, diabetes, or hypoglycaemia." (PMID 31527438, 2019). "The decreased expression of SSTR2 in tumor is associated with lack of response to SST analogs." (PMID 31231308, 2019). "It has been demonstrated that somatostatin and its analogs display antiangiogenic and antiproliferative activity on tumor cells both in vitro and in vivo, highlighting that some neuropeptides and specially its synthetic derivatives could be potentially used as antitumor agents." (PMID 28194370, 2017). "Furthermore, MCoAA-02 could indirectly regulate VEGF on endothelial or tumor cells by inhibiting signaling events downstream of the SST and PEDF receptors, resulting in the suppression of cell proliferation, migration and blood vessel growth." (PMID 27734947, 2016). "Therefore, MCoAA-02 could potentially have an indirect effect in regulating VEGF on endothelial or tumor cells by inhibiting signaling events downstream of the SST and PEDF receptors, which results in the suppression of cell proliferation and migration." (PMID 27734947, 2016). "Several in vitro and in vivo studies have suggested that SST functions as a tumor suppressor gene in human cancers and may inhibit tumor growth through mechanisms that involve the inhibition of growth factors and hormones and a reduction in the vascularization." (PMID 24260078, 2013). "Besides biochemical effects, somatostatin and its analogues also inhibit tumor cell growth." (PMID 22574156, 2012). "Indeed, it has been suggested that somatostatin analogues may control tumor growth in nearly all patients, since very few patients experienced persistent tumor enlargement during medical therapy." (PMID 22574156, 2012). "Altogether, our results provide novel information on the status of the somatostatin system in PPGL and identify new potential therapeutic tools selectively targeting somatostatin receptors on this refractory tumor." (PMID 41928014, 2026). "Based on the suspected tumor type, laboratory tests commonly assess hormone levels such as insulin, gastrin, glucagon, vasoactive intestinal peptide (VIP), and somatostatin to identify functioning PANNETs." (PMID 40427145, 2025). "Cultures of the primary tumor were positive for many neuroendocrine markers over several passages, including CgA, NSE, somatostatin, SSTRs, and gastrin, among others." (PMID 39649120, 2024). "Although frequently heterogeneous in terms of primary tumor site, clinical presentation, and behavior over time, NET are typically slow-growing and usually express somatostatin receptors (SST), mostly type 2." (PMID 38581469, 2024). "Among peptide hormones, agonistic analogs of GnRH and somatostatin can inhibit tumor growth, while in other cases, such as with α -MSH, only antagonists can evoke tumor growth inhibition in an autocrine/paracrine manner." (PMID 38256168, 2024). "Tumor-to-blood ratio (TBR), defined as the ratio between the SUVmean of the tumor divided by the SUVmean of the left ventricle or aortic blood pool, was found to correlate to NET cells’ Ki67 and to reflect SST expression better than SUVmax." (PMID 38581469, 2024). "Functional tumours are uncommon and produce hormones and peptides including insulin, gastrin, vasoactive intestinal peptide (VIP), glucagon, somatostatin, and serotonin." (PMID 39246612, 2024). "Four genes (UGT2B17, SST, CRYGB, and THRSP) were downregulated in tumor samples, whereas eighty genes were increased." (PMID 36785673, 2023). "Shared decreased protein-coding genes across all tumor types included FOXP2, GABRA1/2/4/5, NRGN, SST, and SYNPR." (PMID 36865335, 2023). "The researchers found that the combination of SST and SSTR2 inhibits cytokine release from immune cells and impacts the tumor microenvironment (TME)." (PMID 37900156, 2023).
tumor (continued). "Of note, the results revealed that BIRC5, BUB1, and TPX2 were positively correlated with tumor purity, whereas GNG7 and SST were negatively correlated with tumor purity." (PMID 36863706, 2023). "The presence and distribution of SST and SSTR subtypes in control and thyroid gland with tumour have been most controversial." (PMID 38203605, 2023). "This property could indicate the possibility to regulate other tumour growth through targeting the SST signalling pathway, especially since SSTRs are expressed also in breast, thyroid, prostate cancer tissues, glioma, hepatocellular carcinoma, and other tumours." (PMID 35163374, 2022). "SST expression is generally lower in BP-NEN than in GEP-NEN and has distinct patterns between the two tumour types." (PMID 36042228, 2022). "The capability of the 161Tb- and 177Lu-labeled somatostatin (SST) analogues to reduce viability and survival of SSTR-positive AR42J tumor cells was investigated in vitro." (PMID 34625828, 2022). "When comparing results from the TMA and the whole-block tumour samples for MTC, generally higher SST and CXCR4 expression rates were observed with the whole blocks." (PMID 35799158, 2022). "As in the whole-block MTC samples, the extent of SST and CXCR4 expression in the TMA tumour samples was very low overall." (PMID 35799158, 2022). "Further prospective studies, in larger tumor series, are needed to study the correlation of SSTR expression profile with 68Ga-labeled SST and [18F]F-FDG PET/CT for the personalized management of PNEN patients." (PMID 35008325, 2021). "In the present series, we observed a differential SST expression pattern in OSCC tissues (SST2 >> SST5 > SST4 > SST1 > SST3), compared to their corresponding adjacent non-tumor tissues (SST1 > SST2 > SST5 > SST4 > SST3)." (PMID 34638313, 2021). "In summary, this report assesses the expression levels of all five SST subtypes in OSCC by qPCR, and it is the first series to compare the expression levels of each receptor between OSCC and control (adjacent non-tumor) tissues." (PMID 34638313, 2021). "Downregulation of COX-2 expression and function in CRC cells by SST is thought to occur through activation of SST3 or SST5, and these effects contribute to the antiproliferative effects of SST on tumor cells." (PMID 34829972, 2021). "Potential therapeutics with promising anti-tumor effects include targeted cytotoxic SSAs in combination with chemotherapeutics, SST2 agonists, and SST antagonists." (PMID 34829972, 2021). "In patients with PDAC and diabetes, increased serum glucagon, somatostatin and islet amyloid polypeptide (IAPP) levels were found to revert to normal following tumour resection, indicating an influence of tumour cells on the profiles of these hormones." (PMID 34680372, 2021). "Somatostatin receptor expressing tumor volume (SRETV), defined as tumor volume with higher [68Ga]Ga-SST uptake than 50% of SUVmax within the volume of interest for each lesion, demonstrated prognostic value of survival." (PMID 32151049, 2020). "In full void, methylation levels of GHSR, miR-129, PRDM14, SST and ZIC1 were significantly correlated to the matched tumor tissues." (PMID 32252299, 2020). "For urine supernatant, there was a significant correlation between methylation levels of MAL, PHACTR3, PRDM14, SST and ZIC1 and the matched tumor tissues." (PMID 32252299, 2020). "Because of the specific binding to SST of these radiopharmaceuticals and the overexpression of SST in NETs, SST imaging via PET has high sensitivity and specificity for detecting tumor lesions." (PMID 32335823, 2020). "A large body of TCGA and GEO data confirmed SST hypermethylation and downregulation in PDAC and showed a similar effect in a broad spectrum of other tumor entities." (PMID 32243066, 2020).